CD40 (CD40 molecule)
Diseases named in the same sentence as CD40 in open-access papers (continued):
Sharing a sentence is not in itself a finding about the gene and the disease.
pancreatic cancer (continued). "It is noteworthy that, the two scFv sequences (i.e., anti-CD40 scFv and anti-CLDN18.2 scFv) possess the ability to recognize both human macrophages and pancreatic cancer cells." (PMID 38468289, 2024). "Thus, agents that can activate CD40 may be beneficial to pancreatic cancer patients." (PMID 38672552, 2024). "To enable immunotherapy in a mouse model with tumor, we employed artificially constructed “cold” pancreatic cancer cells expressing high levels of CLDN18.2 and isolated macrophages from CD40-humanized transgenic mouse." (PMID 38468289, 2024). "CD40 expression was then evaluated on the large available patient cohorts for three of the tumor types demonstrating high CD40 positivity rate; NSCLC, ovarian and pancreatic cancer." (PMID 36894898, 2023). "Our results mirror those from other preclinical models which showed CD40 agonism and CBT synergizing in treating mice with colon tumors and significant prolonged survival in a pancreatic cancer model treated with a DC vaccine paired with CD40 agonism." (PMID 37548358, 2023). "In this study, adenoviral-mediated endogenous expression of (m) CD40L activated the CD40/CD40L checkpoint and improved dendritic cells-mediated cytotoxicity of effector cells against cholangiocarcinoma, pancreas carcinoma and colorectal carcinoma in vitro." (PMID 33180184, 2021). "Moreover, various alternative approaches for the treatment of pancreatic cancer are being explored to establish new treatment options and therapeutics i.e., gentamicin in combination with immunotherapy (a monoclonal antibody against CD40) or metabolic inhibitor CPI-613 (Devimistad)." (PMID 32512790, 2020). "Even if anti-CD40 antibodies may not only target TAM and DCs, but also other CD40-expressing cells such as endothelial cells, in combination with gemcitabine, CD40 agonists have already been shown to induce clinical responses in patients with surgically incurable pancreatic cancer." (PMID 31354719, 2019). "We report here that a CD40 agonist antibody transformed the TME and promoted systemic anti-tumour immune activation in a mouse orthotopic pancreatic tumour model, Pan02." (PMID 26918344, 2016). "Recently, it was reported that CD40 activation on macrophages released interferon-γ and CCL2 and induced MMP-dependent fibrosis degradation in pancreatic carcinoma, resulting in the enhanced chemotherapy efficacy." (PMID 27655706, 2016). "This study compares the effects of combining FLASH-RT or CONV-RT, each with or without LIFE Biomaterial loaded with an anti-CD40 antibody, on the growth of syngeneic subcutaneous pancreatic tumors in wild-type C57BL/6 mice." (PMID 41155910, 2025). "The CLARITY biomaterial was evaluated for its therapeutic capability when loaded with either 100 μg_anti-CD40 monoclonal antibody or 800 μg_Caflanone drug against a no-treatment group of C57BL6 mice bearing subcutaneous pancreatic tumors." (PMID 39452584, 2024). "It has been reported that CD40 and PLAU are involved in pancreatic cancer pathogenesis." (PMID 37024802, 2023). "CD40 antibodies have been shown in preclinical studies to improve responses to combinations of chemotherapy or radiotherapy with anti-PD1 and anti-CTLA4 in pancreatic cancer, one of the tumors most resistant to immunotherapy." (PMID 37620372, 2023). "Sustained low‐dose agonist CD40 monoclonal antibody delivered via NDES effectively triggers anti‐tumor immune response in immunosuppressive pancreatic tumor microenvironment without treatment‐related adverse events." (PMID 36658712, 2023).
pancreatic cancer (continued). "In a mouse model of pancreatic cancer, the density of the ECM was shown to be reduced after an anti-CD40 agonist treatment, through the activation of matrix metalloproteinases production by TAM, which may facilitate the motility of T cells." (PMID 31354719, 2019). "Thus, through an indirect effect, CD40 activating monoclonal antibodies activate CD8+ T cells and potentially can reverse the immunosuppressive environment observed in pancreas cancer." (PMID 29891787, 2018). "Pancreatic cancer is a heterogenous disease with multiple exomic genetic alterations in about 12 key cellular signaling pathways (e.g., Poly (ADP-ribose) polymerase inhibition, CD40 activation, hedgehog signaling inhibition, and RET inhibition)." (PMID 29361690, 2018). "In a spontaneous mouse pancreatic tumour model, the addition of gemcitabine did not improve the anti-tumour efficacy of CD40 agonism." (PMID 26918344, 2016). "Engagement of CD40 permitted to overcome resistance to anti-PD1 therapy through repolarization of macrophages towards an inflammatory phenotype, leading to strong CD8 T cell activation in a intrahepatic cholangiocarcinoma genetic mouse model of bladder and pancreatic cancer." (PMID 34572013, 2021). "We tested a similar regimen of single dose SBRT (10Gy) with or without intratumoral anti-CD40 in mice bearing palpable KPC pancreatic tumors on each flank, and again observed significant regression of non-treated tumors and increased overall survival in combination treated mice." (PMID 30245691, 2018). "We use two mouse models of pancreatic cancer to show that a single dose of stereotactic body radiation therapy (SBRT) synergizes with intratumoral injection of agonistic anti-CD40, resulting in regression of non-treated contralateral tumors and formation of long-term immunologic memory." (PMID 30245691, 2018). "CD40-activated macrophages infiltrated the tumor and became not only tumoricidal but also facilitated the depletion of tumor stroma, inducing tumor regressions in some patients as well as in a genetically engineered mouse model of pancreatic cancer." (PMID 23641216, 2013). "The ability of CD40 agonists to stimulate stromal modulation and reorganization via macrophage activity suggests other therapeutic modalities could be enhanced without the immunosuppressive stroma characteristic of pancreatic tumors." (PMID 32843336, 2020). "CD40 stimulation to regulatory B cells is derived from cognate CD4+ T cells in EAE, but it is not known in pancreatic cancer where antigen-specific T cell responses are not as prevalent." (PMID 35046933, 2021).
colitis (86 papers, 2010 to 2025). Inflammation of the colon. "In an experiment with Il‐23‐/WTRag−/− mice, neutralization of endogenous IL‐22 with anti‐IL‐22 antibody after anti‐CD40 injections leads to a significant reduction in weight loss, colitis scores, and colon pathology." (PMID 38363052, 2024). "The authors have observed that nov038/CD40 administration caused inhibition in the development of TNBS colitis." (PMID 37242677, 2023). "The results of this investigation demonstrated the efficacy of delta-9-tetrahydrocannabinol in attenuating anti-CD40-induced colitis and colitis-associated colon cancer." (PMID 37065370, 2023). "In an experimental mouse model of colitis induced by α-CD40 Ab injection into Rag2-deficient mice it was shown that ILC3s contribute to the pathology by IL-23-driven release of IFN-γ13,15,16." (PMID 34341503, 2021). "In recombination-activating gene 2 (Rag2)-deficient mice treated with α-CD40 antibodies (Abs) to elicit colitis, the release of IL-23 by myeloid cells activates colonic ILC3s to switch to pro-inflammatory IFN-γ production, thereby promoting the disease." (PMID 34341503, 2021). "Since the anti-CD40 agonist antibody had only been shown to induce colitis in T and B deficient strains, we next confirmed that it also induced intestinal inflammation in WT C57BL/6 mice." (PMID 32155151, 2020). "Future studies will help elucidate potential preventative and therapeutic measures surrounding CD40 that can be used to combat MC-LR GI toxicity in more vulnerable and susceptible populations, such as those with pre-existing colitis." (PMID 32498446, 2020). "Neutralization of IL-22 results in a significant reduction in the weight loss and colitis scores caused by the anti-CD40 injection, while IL-22 administration has been shown to drive more severe mucosal damage." (PMID 32670290, 2020). "CD40 agonist antibodies are known to induce systemic inflammation and colitis in immune deficient mice." (PMID 32155151, 2020). "Here we demonstrate that the susceptibility to develop colitis by CD40-signalling in DCs is background-dependent." (PMID 30653608, 2019). "For this purpose, we used a model of innate colitis in which intestinal inflammation is induced in T- and B-cell-deficient mice by the administration of an agonistic CD40 Ab." (PMID 29343433, 2018). "To test if these changes are caused by the CD40-fusion protein or by secondary inflammatory effects due to colitis, we also analysed mice treated with ABX or on Rag1−/− background, which are free of colitis." (PMID 28276457, 2017). "In this report, we provide evidence that TL‐deficiency causes increased inflammation in a model of colitis induced with anti‐CD40 antibodies." (PMID 28474503, 2017). "E-cadherin+ DCs express high amounts of CD40, and addition of an agonistic CD40 mAb is sufficient to induce colitis in B6 Rag1−/− mice, which is associated with the marked accumulation of E-cadherin+ DCs in the intestine and MLN." (PMID 20399121, 2010). "Notably, pharmacological inhibition of CD40 signaling significantly attenuated Fn-aggravated colitis, as evidenced by less body weight loss, reduced DAI scores, preserved colon length, and improved histological features." (PMID 41567217, 2025). "Also, treatment of anti‐CD40‐induced colitis mice with I3C caused an increase in the expression of AhR and mBD‐1." (PMID 40410944, 2025). "Based on the literature, including the effects of GPR183 deficiency on Group 3 innate lymphoid cells (ILC3) in the anti-CD40 induced colitis model, we investigated the effect of GPR183 deficiency on innate immune cells and other cell types in the T cell transfer model." (PMID 36389671, 2022). "This is of critical importance as a pathogenic role of ILC3 has been shown in colitis mouse models with H. hepaticus and anti-CD40 antibody driven colitis and even IBD patients and CCR6+ ILC3 have been linked to enhanced airway hyperreactivity in an obesity model." (PMID 34795671, 2021).
colitis (continued). "Thus, our data reveal that Hh is rapidly provoking strong intestinal inflammation in DC-LMP1/CD40 mice, indicating that this bacterial stimulus in the context of CD40-transgene expression is causing the development of early onset colitis." (PMID 33550886, 2021). "The pathogenic role of IL-22 in CD40-triggered colitis may depend on the presence of microbial factors that also influence IL-17A production in the intestine." (PMID 26780670, 2016). "A more complex scenario emerged however from studies in chronic CD45RB (high) CD4+ T cell transfer and anti-CD40 antibody-induced acute innate colitis models in Rag1-deficient mice showing that IL-23R signaling in ILCs3 is protective in the former and pathogenic in the latter." (PMID 25061260, 2014). "In contrast, control or anti-CD40-induced colitis mice treated with I3C showed lower levels of Muribaculum intestinale, Prevotella disiens, Prevotella intermedia and Acetatifactor muris." (PMID 39894796, 2025). "Similar to I3C, our data showed that TCDD upregulated AhR, CYP1A1 and mBD‐1 in CECs from control and colitis (anti‐CD40/ DSS‐ induced) animals." (PMID 40410944, 2025). "Further focusing on AhR and mBD‐1, the data showed that the epithelial cells from anti‐CD40‐induced colitis mice exhibited decreased levels of AhR and mBD‐1 mRNA and protein expression when compared to the controls." (PMID 40410944, 2025). "We analyzed microbiome composition in the ileal contents of control and anti-CD40 or DSS-induced colitis animals by using the 16S rRNA sequencing." (PMID 39894796, 2025). "We cocultured a bacterial population from the ileal contents of normal, anti-CD40-induced colitis, and anti-CD40+I3C treated mice with CECs MC38 for 24 hours and examined AhR and BD1 mRNA and protein expression." (PMID 39894796, 2025). "Cladogram and LDA score depicting enriched microbial taxa between control versus Anti‐CD40 colitis groups and between Anti‐CD40 versus Anti‐CD40+I3C groups." (PMID 40410944, 2025). "Our analysis found that anti-CD40 or DSS-induced colitis mice had enrichment of Bacteroidia phylum members, which exacerbates intestinal inflammation by producing LPS." (PMID 39894796, 2025). "To further examine the contribution of CD40 signaling to Fn-mediated colitis in vivo, we employed the TNBS-induced murine model with Fn gavage and TRAF-STOP intervention." (PMID 41567217, 2025). "In IELs, sulfasalazine-treated WT colitis mice exhibited a significant increase in CD40+ cell frequencies compared to untreated WT colitis mice (p < 0.05)." (PMID 40977735, 2025). "Cladogram and LDA score and Bar plot demonstrated that anti‐CD40‐induced colitis mice showed a decrease in many members of the Firmicutes phylum (gram‐positive bacteria) and an increase in the members of Bacteroidia phylum (gram‐negative bacteria)." (PMID 40410944, 2025). "Here, we integrate clinical analyses, murine colitis models, and mechanistic studies to investigate how Fn promotes CD40-dependent DC activation and drives Th17/Treg imbalance in CD." (PMID 41567217, 2025). "Using RNA sequencing analysis, we identified more than 200 robust genes whose expression was induced in anti‐CD40‐mediated colitis in CECs, and which were reversed following treatment with I3C, as shown in the heatmap." (PMID 40410944, 2025). "The treatment of anti‐CD40 colitis mice with I3C reduced the overall colitis with reversal of weight loss, colon length, macroscopic score, and gut leakage as evidenced by decreased FITC‐dextran levels." (PMID 40410944, 2025). "We also observed similar results in intestinal epithelial cells (IEC) from control and colitis (anti‐CD40/ DSS‐ induced) animals." (PMID 40410944, 2025). "Cladogram and LDA score generated using LEfSe depicted differentially enriched microbial taxa from the phylum to the genus level between control, anti-CD40 or DSS-induced colitis." (PMID 39894796, 2025).
colitis (continued). "In IELs, administration of the probiotic mixture to mice with colitis also significantly decreased the frequencies of CD40+, CD83+, and CD80+ cells (p < 0.05)." (PMID 39201260, 2024). "In the anti-CD40 antibody and H. hepaticus induced models of innate colitis, RoRγt-dependent ILC3 are required for development of colitis." (PMID 38512959, 2024). "Adoptive transfer experiments revealed that both WT and Il10−/− Tregs significantly suppressed anti-CD40 agonistic antibody-induced colitis." (PMID 39379604, 2024). "The innate colitis in anti-CD40 or H. hepaticus treated mice is acute and systemic, whereas the colitis in TRAG mice is chronic and limited to the colon." (PMID 38512959, 2024). "Mice with colitis showed higher frequencies of CD40+ cells (p < 0.05) and CD80+ cells (p < 0.01) in the PBL compared to controls." (PMID 39201260, 2024). "ILC1 can release interferon (IFN)-γ to induce inflammation in certain colitis models (Rag1−/− mice treated with anti-CD40) and patients with CD." (PMID 37554552, 2023). "The depletion of intraepithelial ILC1 can ameliorate symptoms in certain colitis models (Rag1−/− mice treated with anti-CD40)." (PMID 37554552, 2023). "On the other hand, in ILCs-related colitis models such as CD40 colitis, IL-10 colitis, T-bet (-/-) Rag2 (-/-) ulcerative colitis (TRUC), GPR183 is one of the pathogenic mechanisms." (PMID 37720208, 2023). "PAFR was evaluated in dextran sodium sulfate exposed mice and anti-CD40 colitis mice, and the results showed that mice in both IBD models had increased levels of neutrophils and a downwards trend in PAFR expression." (PMID 36624474, 2023). "In particular, Bifidobacterium longum alleviated dextran-sulfate-induced colitis through CD40- and CD80-mediated IL-12 production in intestinal epithelial cells." (PMID 36558497, 2022). "Accordingly, they exacerbate chronic intestinal inflammation in mouse models of CD40-triggered colitis or induce colitis-like pathologies in response to infection." (PMID 36052086, 2022). "In a mouse model of colitis initiated by innate immune activation with anti-CD40 mAb, GPR183 was important for the localization of ILC and for inducing inflammation." (PMID 36389671, 2022). "Microcystin-leucine arginine (MC-LR) exacerbated colitis through CD40 and CD40 knockout effectively attenuated the role of MC-LR in mice with pre-existing colitis." (PMID 36531989, 2022). "The anti-CD40 colitis model is run on a RAG-/- background, we therefore first generated NFAM1+/+ RAG-/- and NFAM1-/- RAG-/- mice." (PMID 35095847, 2021). "Lastly, to assess the role of NFAM1 in IBD, we compared development of anti-CD40 induced colitis in NFAM1+/+ and NFAM1-/- mice." (PMID 35095847, 2021). "In this study, we identified the murine commensal Helicobacter hepaticus as a driver of pathogenesis in a CD40-mediated model of colitis." (PMID 33550886, 2021). "In the present study, we focused on microbial-host interactions in the CD40-mediated colitis model to determine how the intestinal microbiota modulates the host immune response." (PMID 33550886, 2021). "Only in some ILC3 cells involved colitis models, such as anti-CD40 and CD45RBllow transferred colitis models, IL-22 plays a pathogenic role." (PMID 32670290, 2020). "Our results are in contrast to the abrogation of acute and chronic innate colitis upon ILC depletion in an anti‐CD40 model." (PMID 32567222, 2020). "Our findings suggest for the first time that MC-LR acts through a CD40-dependent mechanism to exacerbate colitis." (PMID 32498446, 2020). "We further demonstrated that the reduction of CD40 expression in the immune system effectively prevented disease induction in the anti-CD40 agonist antibody-induced colitis model." (PMID 32155151, 2020). "Based on 800CW permeability in the anti-CD40 colitis model, where there is inflammation but minimal epithelial erosion/disruption, we further explored the relationship between mucosal inflammation and gut permeability." (PMID 32170183, 2020).